PTCH1 (patched 1)
Diseases named in the same sentence as PTCH1 in open-access papers (continued):
Sharing a sentence is not in itself a finding about the gene and the disease.
medulloblastoma (continued). "In the SHH-activated medulloblastoma cases, 2 SHH pathway specific mutations in SUFU (MB_5) or PTCH1 (MB_2) were detected." (PMID 32758285, 2020). "The treatment with 5′-Aza-dc in rhabdomyosarcoma and medulloblastoma showed a decrease in PTCH1 gene methylation." (PMID 33396427, 2020). "Hypermethylation at the PTCH1 promoter region has been described in rhabdomyosarcoma, medulloblastomas, and breast cancer, astrocytoma and medulloblastoma cell lines contributing to HH signaling activation." (PMID 33396427, 2020). "The PTCH1 promoter region has been shown to be hypermethylated in rhabdomyosarcoma, medulloblastoma, and breast cancer." (PMID 33396427, 2020). "Formation of BCC in Gln-iPSC-derived teratoma was also expected because both sporadic and familial BCCs are often accompanied by LOH of the PTCH1 gene as is the cases of medulloblastoma." (PMID 32436863, 2020). "are also more likely to differentiate toward neurons, and knockout of Ptch1 in NEPs generated tumors resembling medulloblastoma." (PMID 31204176, 2019). "In the neural field, CD133 and CD15 have been reported to label stem cells and GCPs, respectively, which can initiate tumorigenesis in Ptch1 deleted models of medulloblastoma." (PMID 30657775, 2019). "Here we sought to utilise CD antibody expression to identify and isolate TIC populations in Ptch1 deleted medulloblastoma, and determine if these antibodies can help classify the identity of human medulloblastoma subgroups." (PMID 30657775, 2019). "In our Ptch1 model of medulloblastoma we observed a CD133 expression profile similar to previous reports that have identified CD133+ cells in glioblastoma and medulloblastoma." (PMID 30657775, 2019). "As a putative tumour-propagating cell marker, elevated CD24 expression has been documented in lung, breast, ovarian and brain cancers, and has been affiliated with high Shh/Ptch1 pathway activity in both colorectal cancer and medulloblastoma formation." (PMID 30657775, 2019). "In contrast, CD15 and CD133 have been reported to be expressed on Ptch1 deleted medulloblastoma and have previously been identified as tumour initiation markers in both medulloblastoma and gliomas." (PMID 30657775, 2019). "Using a fluorescence-activated cell sorted (FACS) CD antibody panel, we identified CD24 as a marker of TICs in Ptch1 deleted medulloblastoma." (PMID 30657775, 2019). "To this end we wanted to further characterise the expression of CD24 on Ptch1 deleted medulloblastoma." (PMID 30657775, 2019). "In general, canonical activation of HH-GLI signaling occurs in cancers with mutations in PTCH1 and SMO, such as BCC and SHH-type medulloblastoma, most of which are sensitive to SMO antagonists." (PMID 31244888, 2019). "Recently CD15 has been identified as a marker of medulloblastoma-initiating cells in Ptch1+/- mice and its expression is correlated with a poor prognosis in human medulloblastoma patients." (PMID 30657775, 2019). "Here we report a cell surface CD antibody screen on a Ptch1 deleted model of medulloblastoma, in which we compared expression profiles with developing post-natal day 7 wild type granule cell precursors and adult wild type cerebella." (PMID 30657775, 2019). "Of these subgroups, SHH remains one of the most studied tumour groups due to the ability to model medulloblastoma formation through targeted deletion of the Shh pathway inhibitor Patched1 (Ptch1)." (PMID 30657775, 2019). "Co-immunohistochemistry/in situ hybridisation for the S-phase marker PCNA identified discrete “islands” of CD24+/PCNA+ cells in Ptch1 deleted medulloblastoma, while adult wild type cerebella were predominantly PCNA-/CD24-." (PMID 30657775, 2019). "For these experiments, we utilized the PZp53 murine medulloblastoma cell line, a line derived from a mouse medulloblastoma heterozygous for PTCH1 and null for p5367." (PMID 31541170, 2019).
medulloblastoma (continued). "Recently, it was reported through the use of murine models of medulloblastoma that a cerebellar stem cell (SC) is a TIC population in Ptch1 deleted medulloblastoma." (PMID 30657775, 2019). "GFAP-cre mediated Ptch1 deletion (Ptch1lox/lox;GFAPCre) results in an aggressive medulloblastoma of the cerebellum that begins during postnatal neurogenesis and leads to a 100% mortality rate by approximately three weeks of age." (PMID 30657775, 2019). "This study reports the use of CD24 and CD15 to isolate a GCP-like TIC population in Ptch1 deleted medulloblastoma, and suggests CD24 expression as a marker to help stratify human WNT tumours from other medulloblastoma subgroups." (PMID 30657775, 2019). "In conjunction with CD15, proliferating CD24+/CD15+ granule cell precursors (GCPs) were identified as a TIC population in Ptch1 deleted medulloblastoma." (PMID 30657775, 2019). "Conditional knockout of Ptch1 in GNP cells led to the formation of medulloblastoma in all mice by 3 months of age, confirming that GNP cells are susceptible to oncogenic transformation in the context of SHH overactivity." (PMID 31204176, 2019). "We chose to work with cells derived from the GFAPcre mediated Ptch1 conditional mutant mouse (Ptch1lox/lox;GFAPcre), which develop medulloblastoma with 100% incidence by four weeks of age." (PMID 30657775, 2019). "Smoothened, a GPCR-like receptor, is activated by SHH binding to the Smoothened inhibitor, Patched1 (PTCH1) and is important in cerebellar development and in medulloblastomas, whose origins are in the developing cerebellum." (PMID 31554835, 2019). "In this study no distinct expression profiles were observed with CD133 and CD24 co-staining, indicating that CD24 expression was not correlative with CD133 expression when identifying stem-like cells in Ptch1 deleted medulloblastoma." (PMID 30657775, 2019). "Originally, the HH-GLI signaling pathway was targeted at the level of SMO, in an attempt to bypass the inactivating PTCH1 and activating SMO mutations often found in Hedgehog-associated tumors like medulloblastoma and basal cell carcinoma." (PMID 30158435, 2018). "For example, a rare population of CD15-positive cells identified in human medulloblastomas and from a Ptch1+/− medulloblastoma mouse model also express ATOH1 (also known as MATH1), and so resemble granule neuron precursors rather than stem cells." (PMID 29759978, 2018). "Saridegib was shown to reduce growth of medulloblastoma allografts and chondrosarcoma xenografts and to prolong survival in an aggressive Ptch1-null medulloblastoma model." (PMID 30558232, 2018). "Compound 1 has been shown to inhibit proliferation of rat cerebellar granule cells and of murine Ptch1+/− medulloblastoma cells at nanomolar concentrations." (PMID 29396391, 2018). "Accordingly, transgenic mice with loss of PTCH1 or gain of function of SMO develop BCCs and medulloblastomas." (PMID 29695137, 2018). "Loss of PTCH1 is associated with ~70% of BCCs and 45% of SHH-subtyped medulloblastomas whereas the SMO mutations (such as the constitutively active SMO-M2 [W535L) mutation] is less frequently found in these diseases." (PMID 29348431, 2018). "Decitabine and VPA both induced apoptosis and the combination increased their effects both in vitro and in vivo on leukemic cells and on medulloblastoma and rhabdomyosarcoma that develop in Ptch1 (Protein patched homolog 1) knockout mice." (PMID 28671573, 2017). "These compounds block the Hh pathway through the union of the ligand Robotnikinin, a compound able to bind to the SHH ligand and block its union to PTCH1 in medulloblastoma, BCC, pancreatic and prostate cancer." (PMID 28948003, 2017). "Heterozygous Ptch1 mice developed tumors on the surface of the cerebellum, which closely resemble human medulloblastoma." (PMID 29186899, 2017).
medulloblastoma (continued). "Using PERK heterozygous deficient mice, our previous study showed that the decreased ISR reduces the incidence of medulloblastoma in Ptch1+/− mice by enhancing pre-malignant GCP apoptosis during cell transformation." (PMID 27802424, 2016). "Nevertheless, our previous study showed that PERK heterozygous deficiency does not influence cell proliferation or apoptosis, angiogenesis, or VEGF-A expression in medulloblastoma in adult Ptch1+/− mice." (PMID 27802424, 2016). "Western blot analysis showed that GADD34 homozygous mutation did not alter the level of p-eIF2α and moderately elevated the level of ATF4 in medulloblastoma in Ptch1+/− mice." (PMID 27802424, 2016). "In this study, we sought to better understand the effects of the ISR on the development of medulloblastoma in Ptch1+/− mice by exploiting GADD34 mutant mice." (PMID 27802424, 2016). "Activating mutations in the key components of the SHH pathway PTCH1, SMO and SUFU have been described in medulloblastoma and basal cell carcinoma." (PMID 27825128, 2016). "Western blot analysis showed that GADD34 heterozygous mutation did not change p-eIF2α level, modestly elevated ATF4 level, and moderately increased CHOP level in medulloblastoma in Ptch1+/− mice." (PMID 27802424, 2016). "Clearly, there is no co-relationship between strong CHOP induction and cell apoptosis in either hyperplastic lesions in young Ptch1+/−; Gadd34−/− mice or medulloblastoma in adult mice." (PMID 27802424, 2016). "While we found that the incidence of medulloblastoma in Ptch1+/−; Gadd34+/− mice was noticeably increased as compared to Ptch1+/−; Gadd34+/+ mice (42.6% vs 30.3%), the increase was not statistically significant." (PMID 27802424, 2016). "Collectively, these results showed GADD34 homozygous mutation strongly enhances the ISR and results in the significant decrease of medulloblastoma incidence in Ptch1+/− mice." (PMID 27802424, 2016). "Gross examination and H&E staining revealed that 2 out of 55 asymptomatic Ptch1+/−; Gadd34+/+ mice and 6 out of 45 asymptomatic Ptch1+/−; Gadd34+/− mice developed medulloblastoma, respectively." (PMID 27802424, 2016). "Activation of PERK signaling has been observed in pre-malignant GCPs in young Ptch1+/− mice and in medulloblastoma cells in human patients and animal models." (PMID 27802424, 2016). "We first calculated AGDEX scores of human SHH medulloblastomas and MYCN-amplified neuroblastomas with mouse medulloblastomas (Ptch1+/− model) and mouse neuroblastomas (Th-Mycn model), respectively." (PMID 26818002, 2016). "Medulloblastoma arises from GCPs in the cerebellar EGL of Ptch1+/− mice and exhibits distinct steps of progression." (PMID 27802424, 2016). "Our previous study demonstrated activation of the PERK-mediated ISR in medulloblastoma cells in adult Ptch1+/− mice and in pre-malignant GCPs in young mice." (PMID 27802424, 2016). "Note that reduced Ptch1 activity is also shared by the brain cancer medulloblastoma, where it was shown to contribute to the development of the tumor." (PMID 27798635, 2016). "Collectively, these data suggest that GADD34 mutation, either heterozygous or homozygous, has a minimal effect on cell proliferation, cell apoptosis, and angiogenesis in medulloblastoma in adult Ptch1+/− mice." (PMID 27802424, 2016). "In accordance with this previous study, we showed herein that GADD34 mutation, either heterozygous or homozygous, did not alter cell proliferation, cell apoptosis, angiogenesis, or VEGF-A expression in medulloblastoma in adult Ptch1+/− mice." (PMID 27802424, 2016). "Surprisingly, GADD34 homozygous mutation strongly enhanced the ISR, but significantly decreased the incidence of medulloblastoma in adult Ptch1+/− mice." (PMID 27802424, 2016).
medulloblastoma (continued). "Our previous study showed that the decreased ISR via PERK heterozygous deficiency enhances pre-malignant GCP apoptosis, resulting in the reduction of medulloblastoma incidence in Ptch1+/− mice." (PMID 27802424, 2016). "Surprisingly, the frequency of symptomatic medulloblastoma in Ptch1+/−; Gadd34−/− mice was significantly decreased compared to Ptch1+/−; Gadd34+/+ mice." (PMID 27802424, 2016). "The moderate elevation of CHOP level indicates moderately enhanced ISR in medulloblastoma in Ptch1+/−; Gadd34+/− mice compared to Ptch1+/−; Gadd34+/+ mice." (PMID 27802424, 2016). "We showed here that GADD34 heterozygous mutation moderately enhanced the ISR and noticeably increased the incidence of medulloblastoma in adult Ptch1+/− mice." (PMID 27802424, 2016). "In agreement with this previous study, the frequency of symptomatic medulloblastoma in Ptch1+/−; Gadd34+/− mice was noticeably increased compared to Ptch1+/−; Gadd34+/+ mice." (PMID 27802424, 2016). "H&E staining showed that the morphology of medulloblastoma in both Ptch1+/−; Gadd34+/− mice and Ptch1+/−; Gadd34−/− mice was comparable with Ptch1+/−; Gadd34+/+ mice." (PMID 27802424, 2016). "Nevertheless, the moderately enhanced ISR via GADD34 heterozygous mutation slightly increases the number of hyperplastic lesions in young Ptch1+/− mice and leads to the noticeably elevated incidence of medulloblastoma in adult Ptch1+/− mice." (PMID 27802424, 2016). "SHH medulloblastoma arise from GNPs with aberrant SHH signaling upon deletion of one copy of the SHH receptor Patched (Ptch1+/-) alone or with one or two copies of Cdkn2c." (PMID 26091048, 2015). "In our study, eight genetic variants, annotating three genes involved in the sonic hedgehog signaling pathway (CCND2, PTCH1, and GLI2), were indicted as associated with medulloblastoma risk." (PMID 26290144, 2015). "Downregulation of NRP1 expression has been shown to inhibit motility of medulloblastoma cells from Ptch1 (+/−) mice." (PMID 26097868, 2015). "Eight genetic variants annotating three genes in the sonic hedgehog signaling pathway; CCND2, PTCH1, and GLI2, were found to be associated with the risk of medulloblastoma (Pcombined < 0.05)." (PMID 26290144, 2015). "Ectopic overexpression of all three miRs in cultured medulloblastoma cells from the Ptch1+/−/PtenFloxp/+ transgenic mice (Ptch1 is the receptor for SHH), increased proliferation." (PMID 26170234, 2015). "In contrast, none of the 12 mice transplanted with GNPs purified from the cerebella of P7 miR-17∼92cKO; Ptch1+/−; Cdkn2c+/− mice and expressing Mycn developed medulloblastoma, 180 days post-implantation." (PMID 24928431, 2014). "Another study reported that HDAC1 mRNA and protein levels were upregulated in mouse Ptch1+/− medulloblastoma." (PMID 23951168, 2013). "For example, medulloblastoma and BCC-like skin tumors in Ptch1+/− or Sufu+/− mice can retain the wild-type allele of the genes." (PMID 23951062, 2013).
medulloblastoma (continued). "PTCH1+/− mice develop medulloblastoma, rhabdomyosarcoma and basal cell carcinoma following irradiation, whereas Su(Fu)+/− mice predominantly develop basaloid epidermal proliferations." (PMID 23303278, 2013). "Among them, mutations and deletions of the Shh pathway components PTCH1, Suppressor of fused (SUFU), and RENKDCT11 have been implicated in medulloblastoma." (PMID 23951168, 2013). "Inactivating mutations in PTCH1 or more rarely, activating mutations in SMO have been identified in most sporadic medulloblastomas." (PMID 22349813, 2012). "Together with the sustained proliferation of these cells in combined Ptch1+/− Nos2−/− mice, this effect results in an increased medulloblastoma incidence relative to Ptch1+/− mice and demonstrates a new disease-promoting mechanism in this tumor entity." (PMID 22438824, 2012). "We observed a two-fold higher medulloblastoma rate in Ptch1+/− Nos2−/− mice compared to Ptch1+/− Nos2+/+ mice." (PMID 22438824, 2012). "Deletion of one Ptch1 allele in C57BL/6 mice, which are homozygous for the GC allele, results in a higher incidence of medulloblastomas compared to mice with a mixed genetic background." (PMID 20433698, 2010). "Silencing expression of GLI1 resulted up-regulation of all target genes in the medulloblastoma cell line, while only PTCH1 was up-regulated in astrocytoma." (PMID 21059263, 2010). "Evidence that the Hh pathway is involved in human cancers is exemplified by Gorlin syndrome arising from autosomal dominant mutations in PTCH1 that dramatically increase the risk of advanced basal cell carcinoma (BCC), medulloblastoma and rhabdomyosarcoma." (PMID 21203400, 2010). "Similar upregulation patterns of the Gli1 transcripts were also observed in medulloblastomas from Ptch1+/- mice maintained on a C57BL/6 genetic background." (PMID 20433698, 2010). "To further our understanding of epigenetic regulation, we also monitored the methylation status of the Cyclin D2 and PTCH1 promoters in 14 cell lines and 58 tumor samples derived from medulloblastomas and astrocytomas." (PMID 21059263, 2010). "It is important to note that reports have shown PTCH1 promoter hypermethylation in several cancers, including medulloblastomas." (PMID 21059263, 2010). "We subsequently sought to determine the pattern of PTCH1 transcript expression in 6 medulloblastoma cell lines and 14 primary medulloblastoma samples and observed that 50% of the cell lines and tumor samples showed high expression of PTCH1." (PMID 21059263, 2010). "Our PTCH1 methylation results among the 6 medulloblastoma cell lines identified a methylated peak in only one cell line, D283." (PMID 21059263, 2010). "GLI1 appears to up-regulate PTCH1 expression in both medulloblastomas and astrocytomas, and remaining genes tested, namely, Cyclin D2, Plakoglobin, PAX6, and NKX2.2, only in medulloblastomas." (PMID 21059263, 2010). "Analysis of promoter methylation suggests that epigenetic regulation of Cyclin D2 is stronger in astrocytomas than in medulloblastomas, while epigenetic regulation of PTCH1 is weak in both tumors." (PMID 21059263, 2010). "Mutations in Sonic Hedgehog (SHH) pathway genes (PTCH1, SUFU) are found in approximately 25% of medulloblastomas, and in WNT pathway genes (β-catenin, APC, AXIN) in approximately 15% of the cases." (PMID 18769486, 2008). "Interestingly, PTCH1 and SMO pathogenic mutations are substantially more frequent in sporadic medulloblastoma than SUFU pathogenic mutations are." (PMID 37629084, 2023). "Deleting PTCH1 or inactivating SMO in the GNPs leads to medulloblastoma development." (PMID 37943476, 2023).